FGF21 (fibroblast growth factor 21)
Diseases named in the same sentence as FGF21 in open-access papers (continued):
Sharing a sentence is not in itself a finding about the gene and the disease.
myocardial ischemia (20 papers, 2013 to 2025). A disorder of cardiac function caused by insufficient blood flow to the muscle tissue of the heart. "Importantly, BAT-derived FGF21 has also recently been demonstrated as a cardioprotective factor in C57BL/6J mice subjected to myocardial ischemia/reperfusion injury (I/R), which is a major causative factor in myocardial damage resulting from infarction." (PMID 40149686, 2025). "In acute myocardial ischemia models, FGF21 activates the FGFR1/KLB-ERK signaling pathway in cardiomyocytes, leading to phosphorylation of CREB and upregulation of PGC1α, forming a protective regulatory cascade." (PMID 41234361, 2025). "In acute myocardial ischemia, cardiomyocytes can either secrete FGF21 in the form of paracrine secretion or induce FGF21 secretion from liver and adipose tissue, which acts on cardiomyocytes in an endocrine manner to exert cardioprotective effects." (PMID 36778154, 2023). "FGF21 was found to upregulate glucose transporter-1 (GLUT1) expression during acute myocardial ischemia, thereby improving energy supply to cardiac myocytes, increasing cell migration and decreasing apoptosis (Hu, Cao & Liu, 2017)." (PMID 36778154, 2023). "FGF21 protects the heart from myocardial ischemia and I/R injury by activating the AMPK signaling pathway, and the underlying mechanism is associated with anti-apoptotic effects." (PMID 36293323, 2022). "FGF21 protects the heart from myocardial ischemia and ischemia/reperfusion (I/R) injury by inhibiting apoptosis and inflammation." (PMID 36293323, 2022). "Preconditioning mice with myocardial ischemia elevates FGF21 secretion by liver and adipose tissue, and reduces the activity of caspase 3 through the phosphorylation of PI3K to ultimately reduce myocardial cell death and apoptosis." (PMID 35369322, 2022). "Based on the observation of ischemic arrhythmia in the MI rat model, we further clarify that the protective effect of FGF21 on arrhythmia depends on the pathological process of alleviating myocardial ischemia." (PMID 34630093, 2021). "Earlier, it has been shown that FGF21 can repair myocardial ischemia/reperfusion injury by promoting autophagy." (PMID 34746149, 2021). "Previous studies have indicated that FGF21 inhibited oxidative stress and ER stress-induced apoptosis in myocardial ischemia injury, which was related to the activation of the PI3K/AKT pathway." (PMID 34777697, 2021). "Studies have shown that the secretion of FGF21 in liver tissue increased during myocardial ischemia, and it played a cardioprotective effect through blood circulation." (PMID 34777697, 2021). "Fibroblast growth factor 21 played an important role in liver-cardiac crosstalk during myocardial ischemia by regulating energy expenditure." (PMID 34368135, 2021). "We were interested to decipher the mechanisms of FGF21 induced myocardial protection using pathophysiological models of cardiac ischemia in lean and obese states." (PMID 24498293, 2014). "This investigation also showed the long-term cardioprotective effect of FGF21 in myocardial ischemia/reperfusion injury." (PMID 24067542, 2013). "We evaluated the cardioprotective action of FGF21 based on the TUNEL index in wild-type and FGF21−/− mice at 24 hrs of myocardial ischemia/reperfusion injury." (PMID 24067542, 2013). "We evaluated the influence of FGF21 on the left ventricular (LV) dp/dt and fractional shortening in wild-type and FGF21−/− mice with myocardial ischemia/reperfusion injury." (PMID 24067542, 2013). "First, FGF21 was upregulated in hepatic cells and adipocytes in response to myocardial ischemia/reperfusion injury." (PMID 24067542, 2013). "Here, we demonstrated that the liver and adipose tissue were activated in myocardial ischemia/reperfusion injury to upregulate and release FGF21 for myocardial protection." (PMID 24067542, 2013).
myocardial ischemia (continued). "The present investigation was designed to test a signaling mechanism that mediates FGF21-based myocardial protection in the mouse model of myocardial ischemia/reperfusion injury." (PMID 24067542, 2013). "The reduced miR-145 that was induced by myocardial ischemia/reperfusion injury in rats could mediate the protective role of FGF21 against myocardial damage." (PMID 32178736, 2020). "To date, a question of whether administration of exogenous FGF21 can also induce cardiac protection during myocardial ischemia and if so whether the protection of exogenous FGF21 against myocardial ischemia can be direct to the heart or cardiomyocytes appears." (PMID 27247947, 2016). "It is possible that myocardial ischemia induces FGF21 expression in other organs and tissues." (PMID 24067542, 2013). "In this investigation, we intended to test the hypothesis that FGF21 protects cardiomyocytes from injury via the mediation of the FGFRs/β-Klotho–PI3K–Akt1–BAD signaling network in myocardial ischemia/reperfusion injury." (PMID 24067542, 2013). "In response to myocardial ischemia/reperfusion injury in the mouse, FGF21 was upregulated and released from the hepatic cells and adipocytes into the circulation and interacted with FGFR1 in cardiomyocytes under the mediation of the cell membrane protein β-Klotho, inducing FGFR1 phosphorylation." (PMID 24067542, 2013). "To test this possibility, we assessed the relative expression of FGF21 in the brain, ischemic myocardium, lung, liver, pancreas, spleen, kidney, small intestine, adipose tissue, and skeletal muscle of wild-type mice with sham-operation and myocardial ischemia/reperfusion injury." (PMID 24067542, 2013). "To explore the mechanisms by which circulating FGF21 was increased during early hours of AMI, we set out the experiments using mice model of myocardial ischemia." (PMID 31413360, 2019). "In addition, we found that myocardial FGF21 production and release as well as activation of AMPK-FGF21 axis by heart are robustly induced upon myocardial ischemia in mice, and that activation of AMPK is required for catecholamine- and SFA-induced FGF21 expression in cardiac myocytes." (PMID 31413360, 2019). "Although various growth factors and cytokines were upregulated during myocardial ischemia, the expression and secretion of cardiac FGF21 had no alteration, implying FGF21 induces cardiac protection against myocardial ischemia in an endocrine rather than an autocrine manner." (PMID 27247947, 2016). "As FGF21 interacts with all known protein tyrosine kinase-coupled FGFRs, including FGFR1, FGFR2, FGFR3, and FGFR432, 36, 37, we tested the expression of these FGFRs in cardiomyocytes from wild-type mice with and without myocardial ischemia/reperfusion injury." (PMID 24067542, 2013).
Sepsis (20 papers, 2013 to 2025). Sepsis is defined as life-threatening organ dysfunction caused by a dysregulated host response to infection. "A large increase of serum FGF21 level from baseline is associated with 28-day mortality in ICU patients with sepsis and ARDS." (PMID 34154595, 2021). "An increase in the serum level of FGF21 after ICU admission of patients who have sepsis and ARDS is associated with a significantly increased risk of 28-day mortality." (PMID 34154595, 2021). "Further studies are needed to better delineate the role of FGF21 in conditions associated with inflammation such as sepsis and SIRS." (PMID 23999826, 2013). "Studies in animal models of sepsis-induced critical illness suggested that FGF21 deficiency increased mortality, whereas FGF21 supplementation may decrease mortality." (PMID 37537627, 2023). "Therefore, we studied the impact of both loss of FGF21 and supplementation with an FGF21 analogue on muscle in a mouse model of critical illness induced by surgery and sepsis." (PMID 37537627, 2023). "This confirms that a large increase in the serum level of FGF21, either between the first and second measurements or between the first and third measurements, was strongly associated with 28-day mortality in patients with sepsis and ARDS." (PMID 34154595, 2021). "Notably, our Cox proportional hazards model indicated that an increase in the serum level of FGF21 from the baseline was a significant risk factor for 28-day mortality in the Sepsis + ARDS group." (PMID 34154595, 2021). "Furthermore, the underlying mechanism of the protective effects of FGF21 remains unclear in sepsis, and it may need more studies." (PMID 36440004, 2022). "Their findings indicated that sepsis patients with FGF21 levels below 3,200 pg/ml have a significantly lower mortality rate compared to those with levels above 3,200 pg/ml." (PMID 40799939, 2025). "In a study of sepsis patients, those with low concentrations of FGF21 in the blood had a better prognosis compared those with high concentrations." (PMID 38313013, 2024). "It was found that circulating levels of FGF21 were increased in patients with sepsis and systemic inflammatory response syndrome (SIRS), which suggested a possible role of FGF21 in inflammation." (PMID 37864659, 2024). "The circulating levels of FGF21 were also found to be higher in patients with sepsis and systemic inflammatory response syndrome (SIRS) than in healthy controls." (PMID 37864659, 2024). "This study in a mouse model of critical illness induced by surgery and sepsis, in comparison with healthy pair-fed mice, confirmed that FGF21 rises acutely after the insult and remains elevated throughout the prolonged phase of illness." (PMID 37537627, 2023). "In this model of critical illness, plasma FGF21 acutely rose after the surgery and induction of sepsis, decreased towards the prolonged phase of illness, but remained elevated as compared with levels in healthy pair-fed mice, as in critically ill patients." (PMID 37537627, 2023). "The level of FGF21 was elevated in both mouse models and human patients with sepsis or other critical illnesses." (PMID 36440004, 2022). "Our measurements at admission indicated that increased FGF21, LAC, and SOFA score were associated with poor prognosis in patients with sepsis and ARDS." (PMID 34154595, 2021). "The effect of changes in the serum level of FGF21 on the prognosis of patients with sepsis and ARDS who have hypo-inflammation is a topic that needs further study." (PMID 34154595, 2021). "In this study, we found that the serum FGF21 level at baseline was greater in ICU patients who had sepsis and ARDS than in those who had sepsis alone." (PMID 34154595, 2021). "The Sepsis + ARDS group had a greater baseline SOFA score and serum levels of cytokines and other biomarkers than the Sepsis-only group; the serum level of FGF21 was almost twofold greater in the Sepsis + ARDS group (P < 0.05)." (PMID 34154595, 2021).
Sepsis (continued). "Previous studies demonstrated that the serum level of FGF21 was greater in adults and newborns who had sepsis." (PMID 34154595, 2021). "The large changes in the serum level of FGF21 from admission to the peak of shock reflect the dynamics of pro- and anti-inflammatory factors in patients with sepsis and ARDS." (PMID 34154595, 2021). "In other words, based on measurements at baseline and the peak of shock, we identified the percentage increase of FGF21 as the best predictor of poor prognosis in patients with sepsis and ARDS." (PMID 34154595, 2021). "FGF21 is mainly secreted by the liver in response to injury, systemic inflammation like sepsis, cancer, and kidney dysfunction." (PMID 28582462, 2017). "A possible role of FGF21 in sepsis has been suggested by the observation of increased circulating levels of this hormone during experimental sepsis in mice." (PMID 23999826, 2013). "Here, we show that FGF21 levels were significantly higher in plasma obtained from patients with sepsis and SIRS in comparison with healthy controls." (PMID 23999826, 2013). "Taken together, these results indicate that circulating levels of FGF21 are increased in patients presenting with sepsis and SIRS, and suggest a role for FGF21 in inflammation." (PMID 23999826, 2013). "We also assessed potential correlations between FGF21 and scores of severity of sepsis as well as clinical outcomes." (PMID 23999826, 2013). "FGF21 serum levels were increased by approximately tenfold in patients with sepsis compared with healthy controls." (PMID 23999826, 2013). "The aim of this study was therefore to evaluate the circulating plasma levels of FGF21 in patients with sepsis, SIRS, and in healthy control subjects." (PMID 23999826, 2013). "We measured FGF21 plasma concentrations in 22 patients with established sepsis, in 11 with SIRS, and in 12 healthy volunteers." (PMID 23999826, 2013). "Sepsis is accompanied by glucose and lipid alterations, and FGF21 is considered as a key regulator in glucose and lipid metabolism." (PMID 23999826, 2013). "Further studies are needed to explore the potential role of FGF21 in sepsis as a potential therapeutic target." (PMID 23999826, 2013). "In these conditions with matched age and BMI, plasma FGF21 levels remained significantly increased in patients with sepsis compared with healthy controls (523±954 pg/ml in healthy controls, P<0.001)." (PMID 23999826, 2013). "We also noticed that the evolution of FGF21 plasma levels using serial samples from patients with sepsis was correlated with their clinical evolution, with a decreasing plasma level associated with clinical improvement." (PMID 23999826, 2013). "The aim of this study was to compare FGF21 plasma levels in patients with sepsis, in patients with systemic inflammatory response syndrome (SIRS), and in healthy controls." (PMID 23999826, 2013). "In conclusion, this study is the first to report a systemic release of FGF21 in human sepsis and SIRS, with plasma levels markedly higher than those found in healthy controls." (PMID 23999826, 2013). "This indicates that FGF21 may be an early marker of sepsis, showing raised levels even before other markers do." (PMID 39838305, 2025). "They found that FGF21 levels were significantly higher in sepsis than in controls." (PMID 39838305, 2025). "FGF21 is also protected from the toxic effects of cecal ligation and puncture-induced sepsis." (PMID 39838305, 2025). "Thus, FGF21 is an acute phase reactant with positive effects that protects animals from the toxic effects of LPS and sepsis." (PMID 39838305, 2025). "Later studies tried to determine whether the absolute value of FGF21 and a large, acute increase in FGF21 levels could predict 28-day mortality risk in patients admitted to the ICU with sepsis." (PMID 39838305, 2025).
Sepsis (continued). "This essential component of fibroblast growth factor (FGF) receptor complexes is required for high-affinity binding of endocrine FGF19 and FGF21 to evoke the signaling cascade actively involved in homeostatic maintenance of glucose metabolism and energy expenditure that are dysregulated in sepsis." (PMID 37638006, 2023). "The relationship between increased expression of FGF21 and sepsis may be explained by these findings." (PMID 36440004, 2022). "Besides, FGF21 can predict the prognostic survival for patients with sepsis, and patients with sepsis with FGF21 levels below 3,200 pg/ml had a significantly lower mortality rate than those with levels above 3,200 pg/ml." (PMID 36440004, 2022). "According to previous studies, FGF21 has played an anti-inflammatory role in sepsis." (PMID 36440004, 2022). "The serum level of FGF21 was almost two-times greater in the Sepsis + ARDS group." (PMID 34154595, 2021). "At the physiological level, this may be attributed to the anti-inflammation, anti-apoptotic, and anti-oxidative effect of FGF21 during sepsis." (PMID 34154595, 2021). "Previous studies reported that FGF21 had anti-inflammatory effects during sepsis." (PMID 34154595, 2021). "In this prospective cohort study, we aimed to evaluate whether changes in the serum level of FGF21 predict 28-day mortality of ICU patients who have sepsis and ARDS." (PMID 34154595, 2021). "Determine whether changes in the level of serum fibroblast growth factor 21 (FGF21) can predict the 28-day mortality of ICU patients with sepsis and ARDS." (PMID 34154595, 2021). "However, the exact kinetic of FGF21, particularly in the situation of sepsis, needs to be further explored to better define its role in this clinical situation." (PMID 23999826, 2013). "As high insulin sensitivity has been shown to have a good performance in ruling out sepsis, FGF21 may be a good tool to exclude sepsis in suspicious cases." (PMID 23999826, 2013). "Although we could show a potential role of FGF21 in sepsis and SIRS, our study has some limitations." (PMID 23999826, 2013). "As FGF21 plasma levels increase after sepsis induction in mice, potentially as a counter-regulatory response, it is tempting to hypothesize that FGF21 administration could have the potential to modulate inflammation." (PMID 23999826, 2013). "We analyzed serial samples of FGF21 in three patients with sepsis." (PMID 23999826, 2013). "This highlights the fact that FGF21 may be considered as a biochemical parameter of follow-up in sepsis and a possible marker of recurrence." (PMID 23999826, 2013). "However, our subgroup analysis where age and BMI were matched between patients with sepsis and healthy controls showed that FGF21 plasma levels remained significantly increased in patients with sepsis." (PMID 23999826, 2013). "Interestingly, FGF21 has been reported to be involved in lipopolysaccharide-induced lung injury, and the emerging roles of FGF21 in acute lung injury/acute respiratory distress syndrome, acute myocardial injury, acute kidney injury, sepsis, and other critical diseases are increasingly noteworthy." (PMID 37218012, 2023). "Indeed, our assumption of FGF21 as a stress-modulating factor in early-lactation dairy cows is supported by the results from a mice study that suggested that FGF21 induction was a potential strategy to protect against the toxicity resulting from experimentally induced sepsis." (PMID 36611740, 2022). "However, the relationship of FGF21 with prognosis in patients with sepsis and ARDS is uncertain." (PMID 34154595, 2021). "The second hypothesis may be that CRP and FGF21 are less specific, and are both increased in inflammatory states not linked to sepsis as opposed to PCT, which has been shown to be more specific for sepsis than CRP." (PMID 23999826, 2013). "When evaluated in a sepsis-induced AKI mice model, KMZ@FGF21 exhibited superior antioxidant and anti-inflammatory efficacy, alleviated AKI, and improved renal function recovery." (PMID 38637839, 2024).